PGM5 (phosphoglucomutase 5)
Diseases named in the same sentence as PGM5 in open-access papers (continued):
Sharing a sentence is not in itself a finding about the gene and the disease.
bipolar disorder (1 paper, 2019). A disorder of the brain that causes unusual shifts in mood, energy, activity levels and the ability to carry out day-to-day tasks. "In addition, PGM5 expression is associated with bipolar disorder and heart disease." (PMID 31582909, 2019).
colon adenocarcinoma (1 paper, 2022). "PGM5 was the key enzyme in the glucose metabolism, and its low expression in colon adenocarcinoma was important to regulate the development and invasion of tumor." (PMID 35655081, 2022).
Duchenne muscular dystrophy (1 paper, 2019). Duchenne muscular dystrophy (DMD) is a neuromuscular disease characterized by rapidly progressive muscle weakness and wasting due to degeneration of skeletal, smooth and cardiac muscle. "Abnormal expression and mutation of PGM5 are associated with a number of diseases, including Duchenne’s Muscular Dystrophy and colorectal tumorigenesis." (PMID 30718897, 2019).
fetal growth restriction (1 paper, 2020). A fetus that does not grow beyond the 10th percentile of conventionally accepted weight for gestational age. "We validated the association between preterm fetal growth restriction and circulating EMP1, NR4A2, and PGM5 mRNA in a cohort from Europe." (PMID 32438913, 2020). "Combining EMP1 and PGM5 had 72% sensitivity to detect preterm fetal growth restriction at 90% specificity, and an AUC of 0.92 (95% CI 0.86–0.98)." (PMID 32438913, 2020). "Thus, we have validated the association between preterm fetal growth restriction and increased circulating mRNA coding NR4A2 and EMP1 (and possibly PGM5) in an independent cohort of samples from another continent." (PMID 32438913, 2020).
lymph node metastasis (1 paper, 2019). "Low PGM5 expression was significantly associated with lymph node metastasis (P = 0.041), clinical stage (P = 0.039) and poor survival (P = 0.005)." (PMID 31582909, 2019). "Furthermore, univariate analysis showed that gender (P = 0.026), lymph node metastasis (P < 0.001), clinical stage (P = 0.001) and PGM5 expression (P = 0.001) were significant predictors of overall survival in CRC." (PMID 31582909, 2019).
metastatic disease (1 paper, 2020). "Except for PGM5, the remaining eight genes were also elevated in the patients who have succumbed to metastatic disease." (PMID 32751097, 2020).
triple-negative breast carcinoma (1 paper, 2021). An invasive breast carcinoma which is negative for expression of estrogen receptor (ER), progesterone receptor (PR), and human epidermal growth factor receptor 2 (HER2). "Interestingly, the PGM5 expression in triple-negative breast cancer (TNBC) patients was lower than that in non-TNBC patients." (PMID 33986801, 2021).
cancer (10 papers, 2018 to 2024). A tumor composed of atypical neoplastic, often pleomorphic cells that invade other tissues. "The results show that PGM5 expression had a modest diagnostic value for patients overall (AUC = 0.787) and for patients with different stages of cancer (AUCStageI = 0.782; AUCStageII = 0.773, AUCStageIII = 0.789; AUCStageIV = 0.740)." (PMID 31218127, 2019). "Recent studies indicated that PGM5 is associated with cancer development and progression." (PMID 33986801, 2021). "It remains to be clarified if the downregulation of PGM5 in cancer is a cause or a consequence." (PMID 33287293, 2020). "Phosphoglucosinase-like protein 5(PGM5) converts glucose-1-phosphate (G1P) to glucose-6-phosphate (G6P) and is upregulated in a variety of cancers, primarily as a biomarker to predict the prognosis of cancer patients." (PMID 37204526, 2023). "SLIT3, ABI3BP, MYOCD, PGM5, TNXB and DNAH9 are strongly associated with cancer initiation and progression." (PMID 36451444, 2022). "Among these genes, PGM5 was selected, because it has been found to be related to tumor progression in some cancers." (PMID 34616611, 2021). "Downregulation of human PGM5 has recently been identified as a prominent biomarker in several types of cancer." (PMID 33287293, 2020). "We analyzed the PGM5 expression data in cancerous liver tissues using ROC analysis for all patients, and for patients with different stages of cancer." (PMID 31218127, 2019). "PGM5 may influence cell proliferation, migration and differentiation through mutiple signaling pathways, thus promoting or inhibiting cancer progression, which needs further validation via molecular biologic experiments." (PMID 35819729, 2022). "These previous findings suggest this protein has a role in cell–matrix adherens junctions and the regulation of telomeres during cancer progression, although no previous study has yet directly examined the specific function of PGM5 during the pathogenesis of cancer." (PMID 31218127, 2019). "Only a few studies have been conducted on the expression and role of PGM5 in cancer." (PMID 31582909, 2019). "However, little is known about the expression of PGM5 during cancer pathogenesis." (PMID 31218127, 2019). "As expected, most up-regulated proteins are related to cancer genes, with seven of them known to be enhanced in PCa (SYNM, DES, MYH11, TAGLN, CNN1, LMOD1, and PGM5)." (PMID 38052461, 2024). "Subgroup analysis indicated that PGM5 expression had significant prognostic value for OS in patients with stage I/II cancer (P = 0.0037) and for RFS in patients with stage I/II cancer (P < 0.0001) and grade G1/G2 cancer (P = 0.0039)." (PMID 31218127, 2019). "Moreover, the miR-1224-3p/PGM5 axis regulates the expression of cell cycle- and apoptosis-related genes and the markers of epithelial-mesenchymal transition (EMT), a process involved in migration and metastasis of cancer cells." (PMID 33986801, 2021). "Therefore, PGM5 is not consistently expressed in cancer with different tissue types, and it may be related to the muscle content." (PMID 31582909, 2019).
tumor (10 papers, 2015 to 2026). "Among the neoantigens are well-known genes associated with tumor progression and metastases, such as HAUS3, NSDHL, MAGEA10, FNDC3B, TEAD1, DHX33, PGM5, and MLL2." (PMID 36607962, 2023). "More importantly, we found that patients with a lower PGM5 level in tumor tissues showed much poorer prognosis." (PMID 35819729, 2022). "Administration of anti-miR-1293 significantly reduced miR-1293 expression, accompanied by elevated PGM5 expression in tumor tissues." (PMID 34616611, 2021). "PGM5 expression was frequently lower in CRC tumour tissue than in the adjacent tissue (t = 5.035, P < 0.001)." (PMID 31582909, 2019). "However, in our study, PGM5 was upregulated in tumor, which was potentially related to its key function in aerobic metabolism that was strongly activated in the process of tumor growth and metastasis." (PMID 35655081, 2022). "We found that PGM5 expression was decreased in tumor tissues of LUAD patients." (PMID 34616611, 2021). "This strongly suggested that PGM5 was a novel tumour suppressor in CRC." (PMID 31582909, 2019). "Therefore, we inferred that PGM5 may be involved in the regulation of tumor inflammation and extracellular matrix by regulating metabolism." (PMID 33200655, 2020). "Administration of miR-1293 antagomir reduced tumor volume and staining of Ki-67 and MMP9, but elevated PGM5 expression in vivo." (PMID 34616611, 2021). "Results showed that the downregulation of PGM5 appeared to significantly correlate with higher Gleason score, but not the tumor stage." (PMID 35819729, 2022). "We found that the mean methylation level of ITM2A, GALNTL1, FAM107A, and MFAP4 was significantly higher in tumor tissue while the methylation level of PGM5 was higher in normal tissue." (PMID 33376725, 2020). "Regarding the expression of luminal and basal biomarkers, Layer3.1 tumor presented higher expression of KRT20, a luminal-papillary biomarker, whereas Layer3.2 had higher expression of KRT5, KRT6a, KRT14, and CD44 basal biomarkers, but also PGM5, DES, and SGCD luminal-infiltrated biomarkers." (PMID 41516353, 2026).
PGM5 also shares sentences with these, for which no sentence is quoted: adenocarcinoma (1 paper); clear cell renal cell carcinoma (1); esophageal cancer (1); heart disease (1); lung adenocarcinoma (1); metastatic cancer (1); metastatic prostate carcinoma (1); non-small cell lung carcinoma (1); osteosarcoma (1); placental insufficiency (1); prostate tumors (1).